RHOA (ras homolog family member A)
Diseases named in the same sentence as RHOA in open-access papers (continued):
Sharing a sentence is not in itself a finding about the gene and the disease.
osteosarcoma (continued). "In this report, we found that the K7 of Rab22a-NeoF1, acetylated by p300/CBP while de-acetylated by both HDAC6 and SIRT1, plays a key role in its binding to SmgGDS607, and consequently affects its activation of RhoA and promotion of cell migration, invasion and lung metastasis in osteosarcoma." (PMID 32685017, 2020). "Besides, up-regulation of miR-144 suppressed tumor growth and metastasis of osteosarcoma in vivo and in vitro by directly inhibiting RhoA and ROCK1 expression." (PMID 32351538, 2020). "BMPR2 promoted human osteosarcoma cell invasion and metastasis through the RhoA-Rocklimk2 pathway." (PMID 31889906, 2019). "MALAT1 promotes the progression of osteosarcoma via upregulation of RhoA, ROCK and Rac1." (PMID 31248165, 2019). "We evaluated the RhoA activation in osteosarcoma MG-63 and U2OS cells with RhoA activation assay." (PMID 29213214, 2017). "We also used dominant-negative constructs (DN-RhoA) to knock down RhoA expression in osteosarcoma cells and checked whether Wnt5a-induced cell migration could be inhibited." (PMID 28289332, 2017). "Moreover, BMPR2-depletion decreased osteosarcoma cell invasion and metastasis in vitro and in vivo by the inactivation of the RhoA/ROCK/LIMK2 pathway." (PMID 28938584, 2017). "Moreover, we found that activation of RhoA was involved in the LIMK/cofilin pathway in osteosarcoma cells." (PMID 28938584, 2017). "Next, we used constitute activity constructs (RhoA-CA, RhoA-V14) to elevate RhoA activity in osteosarcoma cells and checked whether the reductive migration rate by ROR2 knockdown could be rescued." (PMID 29213214, 2017). "In addition, the knock-down of DBC1 decreased expression of invasiveness-related signaling such as NFκB, TGFβ and RhoA, and inhibited the migration and invasion activity of osteosarcoma cells." (PMID 26249023, 2015). "In sarcomas, RhoA regulates the motility of osteosarcoma cell lines." (PMID 20606682, 2010). "Additionally, different signaling pathways such as STAT3/c‐Myc signal pathway, JNK signl pathway, PI3k/AKT/mTOR signal pathway, WNT/β‐catenin signal pathway, and RhoA signal pathway can influence the development of osteosarcoma by regulating PCD in osteosarcoma cell." (PMID 38800967, 2024). "Additionally, RhoA expression has been correlated with Ezrin expression in osteosarcoma, where Ezrin expression may modulate RhoA expression." (PMID 37371090, 2023). "Thus, RhoA activation is regulated by Wnt5a signaling in MG-63 osteosarcoma cells." (PMID 28289332, 2017). "We next examined whether RhoA was downstream of PI3K/Akt in human osteosarcoma cells." (PMID 28289332, 2017). "ZA can impair RhoA membrane localization in LM8 cells, causing obvious changes in the ultrastructure of osteosarcoma cells and induce cell apoptosis, which may be one of the underlying mechanisms by which the agent inhibits the development of vasculogenic mimicry by the LM8 cells." (PMID 21718535, 2011). "ZA can prevent RhoA membrane localization in LM8 cells, causing obvious changes in the ultrastructure of osteosarcoma cells and induce cell apoptosis, which may be one of the underlying mechanisms by which the agent inhibits the development of vasculogenic mimicry by the LM8 cells." (PMID 21718535, 2011). "For instance, Rab31 promotes metastasis in gastric adenocarcinoma; moreover, Rab22a-NeoFs increases RhoA-GTP by binding to SmgGDS-607, which is a GTP-GDP exchange factor for RhoA, thereby promoting osteosarcoma metastasis." (PMID 40000633, 2025). "Taken together, these data indicated that anlotinib treatment induced ATG5-dependent autophagy and that inhibition of autophagy enhanced the inhibitory effects of anlotinib on osteosarcoma metastasis through EMT and the RhoA-ROCK-LIMK2 pathway." (PMID 38381883, 2024). "VEGFR2 inhibition by shRNA or by apatinib, a small molecular tyrosine kinase inhibitor, reduced the osteosarcoma cell migration, invasion, and metastatic potential, and downregulated the STAT3 and RhoA/ROCK/LIMK2 pathways." (PMID 36899941, 2023).
osteosarcoma (continued). "In this study, we reveal that STAT3 knockdown attenuates the expression of PD-L2, p-LIMK2 and p-cofilin in osteosarcoma, suggesting that VEGFR2 inhibition suppresses migration, invasion and PD-L2 expression by targeting the STAT3 and RhoA-ROCK-LIMK2 pathways." (PMID 33014879, 2020). "MALAT1 (Metastasis associated in lung adenocarcinoma transcript 1) increases protein levels of RhoA and the downstream ROCK in osteosarcoma." (PMID 31248165, 2019). "MALAT-1 seems to exert its oncogenic function via regulating the Ras homolog gene family, member A (RhoA)/Rho-Kinase (ROCK)-pathway, as downregulation of MALAT-1 reduces protein levels of RhoA, ROCK1 and 2 in osteosarcoma cell lines U2OS and HOS." (PMID 29657304, 2018). "We present the evidence here that ROR2 mediates Wnt5a-induced osteosarcoma cell migration via PI3K/Akt and RhoA signaling." (PMID 29213214, 2017). "Here, we demonstrates that RhoA acts as the downstream of PI3K/Akt signaling and mediated Wnt5a-induced the migration of osteosarcoma cells." (PMID 28289332, 2017). "In conclusion, RhoA acts as the downstream of PI3K/Akt signaling (specific PI3KαAkt1 and Akt2 isoforms) and mediated Wnt5a-induced the migration of osteosarcoma cells." (PMID 28289332, 2017). "Taken together, we demonstrate that RhoA acts as the downstream of PI3K/Akt signaling (specific PI3Kα, Akt1 and Akt2 isoforms) and mediated Wnt5a-induced the migration of osteosarcoma cells." (PMID 28289332, 2017). "Our previous study illuminates that Wnt5a mediates the migration of osteosarcoma cells via elevating the phosphatidylinositol-3 kinase (PI3K)/Akt and RhoA signaling." (PMID 29213214, 2017). "In this study, we demonstrated that RhoA activation acts as the downstream of Wnt5a/PI3K/Akt signaling, and is specifically regulated by PI3Kα, Akt1 and Akt2 isoforms in osteosarcoma cells." (PMID 28289332, 2017). "The silencing of BMPR2 inhibits invasion and metastasis by the RhoA/ROCK/LIMK pathway, and that also indicates a potential therapeutic target for osteosarcoma." (PMID 28938584, 2017). "Our previous study finds that Wnt5a mediates the migration of osteosarcoma cells via elevating the PI3K/Akt and RhoA signaling." (PMID 29213214, 2017). "The supernumerary centrosome phenotype was also observed in S phase-arrested osteosarcoma U2OS cells when the expression of ARHGEF10, RhoA or KIF3B was abrogated by RNA interference." (PMID 19635168, 2009). "Additionally, MALAT1 demonstrated oncogenic functions, increasing osteosarcoma cell growth potentially through the stimulation of the PI3K/AKT and RhoA/ROCK pathway." (PMID 39015175, 2024). "This leads to the activation of ras homolog family member A (RHOA) in its negative recipient osteosarcoma cells, as well as transcription 3 in its recipient macrophages, therefore increasing the M2 phenotype." (PMID 36834471, 2023). "Further studies have shown that PYK2 was enriched in osteosarcoma derived exosomes by binding to the RAB22A-NeoF1 fusion protein, thereby inducing RhoA activation in RAB22A-NeoF1-negative receptor osteosarcoma cells to promote their migration, invasion, and lung metastasis." (PMID 34712664, 2021). "The exosomal PYK2 activates RhoA in its negative recipient osteosarcoma cells and induces signal transducer and activator of transcription 3 activation in its recipient macrophages to increase M2 phenotype." (PMID 33568623, 2021). "Thus, through the tumor cell extrinsic and intrinsic functions of PD-L2, VEGFR2 can affect both osteosarcoma cell metastasis and immune escape through the deactivation of STAT3 and the RhoA-ROCK-LIMK2 pathway." (PMID 33014879, 2020). "PD-L2 knockdown inhibits metastasis through the RhoA-ROCK-LIMK2 and autophagy pathways, which extends our comprehension of the regulatory function of autophagy in tumor cell metastasis and represents a potential therapeutic target in osteosarcoma." (PMID 30886151, 2019).
osteosarcoma (continued). "The lncRNA MALAT1 reduces the protein expression levels of RhoA, ROCK1, and ROCK2, indicating that MALAT1 may promote osteosarcoma cell migration by the RhoA/ROCK pathway; then, MALAT1 increases the number of actin stress fibers in osteosarcoma cells." (PMID 29618386, 2018). "In addition, RhoA and p38 MAPK activation is responsible for simvastatin-induced apoptosis in osteosarcoma cells." (PMID 29743821, 2018). "Notably, both RhoA and MMP-9, which are positively regulated by Skp2 and play a role in osteosarcoma invasion, were suppressed following Skp2 knockdown." (PMID 30250282, 2018). "In conclusion, ROR2 receptor, acting as the upstream of PI3Kα/Akt/RhoA signaling, is required for Wnt5a-induced the migration, not the proliferation of osteosarcoma cells." (PMID 29213214, 2017). "Taken together, our study revealed that BMPR2 functions as a prometastatic oncogene in vitro and in vivo with the activation of the RhoA-ROCK-LIMK2 pathway and may represent a potential therapeutic target for osteosarcoma." (PMID 28938584, 2017). "Recent literature data suggested that in osteosarcoma the panel of expression of PLC isoforms varies in a complex and unclear manner and is related to ezrin, probably networking with Ras GTPases, such as RhoA and Rac1." (PMID 27026853, 2016). "It was demonstrated that PD‐L2 acted as an upstream factor of RhoA‐ROCK‐LIMK2 and inhibited the RhoA‐ROCK‐LIMK2 signaling pathway when PD‐L2 expression was downregulated, which helped to inhibit osteosarcoma cell autophagy and this can inhibit the metastasis of osteosarcoma." (PMID 38800967, 2024). "Moreover, Apatinib inhibits the upstream of STAT3, vascular endothelial growth factor receptor-2 (VEGFR2), to decrease PD-L2 expression through the RhoA-ROCK-LIMK2 axis, eventually, suppressing tumour migration, invasion, and cytoskeletal rearrangement in osteosarcoma." (PMID 36522474, 2023). "Regarding the management of osteosarcoma, preclinical studies have shown that apatinib promotes apoptosis and autophagy through VEGFR2/STAT3/BCL-2 signaling pathways in osteosarcoma cells, as well as attenuates invasion and migration through RhoA/ROCK/LIMK2 pathways." (PMID 36387068, 2022). "Similarly, vimentin depletion leads to increased stress fiber assembly and myosin activity, via RhoA activation by activating RhoA GEF-H1, but without activating FAK in osteosarcoma cells." (PMID 31003495, 2019).
diabetes (54 papers, 2010 to 2025). "The so-called RhoA/ROCK pathway was initially implicated in ventricular fibrosis in a model of type-1 diabetes mellitus." (PMID 28962617, 2017). "We conclude that oxidative stress in diabetes causes a decrease in miR-133a expression leading to an increase in RhoA/Rho kinase pathway and muscle contraction." (PMID 28678840, 2017). "Airway hyperresponsiveness in asthma and vascular hypertension in diabetes were shown to be associated with an increase in RhoA expression." (PMID 28678840, 2017). "Our findings suggest that atorvastatin attenuates diabetes-associated renal injury by reducing ROS generation, RhoA activity and normalizing Akt/GSK3β signaling pathways." (PMID 27649495, 2016). "The results showed that diabetes causes significant activation of RhoA (2-fold) compared to controls that blocked by treatment with FeTPPs." (PMID 21052489, 2010). "Our studies also identified the mechanism underlying the increase in RhoA expression in diabetes." (PMID 28678840, 2017). "The decrease in the expression of miR-133a in diabetes causes the increase in RhoA expression." (PMID 28678840, 2017). "The effect of pre-miR-133a or antagomiR-133a in vitro in smooth muscle treated with HG was similar to that obtained in vivo, suggesting that the expression of RhoA is negatively regulated by miR-133a and a decrease in miR-133a expression in diabetes causes an increase in RhoA expression." (PMID 28678840, 2017). "We tested the hypothesis that atorvastatin, through redox-sensitive and RhoA-dependent mechanisms, attenuates diabetes-associated nephropathy." (PMID 27649495, 2016). "Finally, recent studies have shed light on the pivotal role of the RhoA/Rock pathway (to be discussed in more detail below), which plays a part in diabetes-associated endothelial dysfunction via modulation of eNOS and EDNO levels." (PMID 22013533, 2012). "However, RhoA is also associated to the deleterious effects of diabetes, particularly in mesangial cells, as well as in several organs that are targeted by diabetes." (PMID 21826213, 2011). "Studies have demonstrated that inhibiting rhoA/rho-kinase pathway is beneficial for kidney damage induced by diabetes and renal ischemia." (PMID 39434789, 2024). "While expression or activity of Rab members tends tobe downregulated under conditions that favor the development of diabetes,overactivated RhoA and Rac1 are involved in many of the pathologiesobserved in T2D individuals." (PMID 34236862, 2021). "As the topic of regulation of Rho GTPases has beenwidely summarized recently, here we concentrateon selected inhibitors, directly targeting Rac1 and RhoA, as the connectionsof these with diabetes-related malfunctions are the most broadly reported." (PMID 34236862, 2021). "In diabetes, RhoA and Receptor for advanced glycation endproducts (RAGE) form a complex called RhoA/RAGE, to induce Rho-kinase activation, resulting in the reorganization of the actin cytoskeleton, leading to endothelial cell hyperpermeability." (PMID 31174369, 2019). "Activation of RhoA plays a key role in the development of both peripheral insulin resistance and in the development of microvascular complications of diabetes." (PMID 30972066, 2019). "Many strategies, which inhibit the Rac/RhoA pathway, also reduce microvascular complications in diabetes via a reduction in inflammation and fibrosis." (PMID 30972066, 2019). "Studies using fasudil, a Rho-kinase (ROCK) inhibitor, and a high-fat/low dose streptozotocin rat model of diabetes, implemented the RhoA/ROCK pathway in cardiac fibrosis through decreasing RhoA, ROCK and collagen expression." (PMID 30534081, 2018). "Future studies are warranted to determine the precise role of RhoA/Rho Kinase pathway in impaired coronary perfusion in diabetes." (PMID 29928236, 2018). "The effect of diabetes in vivo and hyperglycemia in vitro on the expression levels of miR-133a and RhoA and on ACh-induced Rho kinase activity and muscle contraction was blocked with NAC." (PMID 28678840, 2017).
diabetes (continued). "Our studies also provide evidence that the decrease in miR-133a expression and increase in RhoA/Rho kinase pathway in diabetes were due to increase in oxidative stress." (PMID 28678840, 2017). "Specifically, in a rat model of type-2 diabetes mellitus that exhibits significant atrial fibrosis, they found increased expression levels of RhoA and its effectors (ROCK1 and ROCK2) at both the mRNA and protein levels." (PMID 28962617, 2017). "From these studies, it appears that upregulation of Ca2+-dependent MLCK activity and RhoA/PKC-dependent inhibition of MLCP is a general mechanism involved in smooth muscle hypercontractility in diabetes." (PMID 28678840, 2017). "In conclusion, the present studies demonstrate that the expression of RhoA is negatively regulated by miR-133a and a decrease in its expression in diabetes leads to an increase in RhoA expression, agonist-induced Rho kinase activity, and muscle contraction." (PMID 28678840, 2017). "Our studies also suggest that oxidative stress in diabetes upregulates RhoA/Rho kinase pathway and smooth muscle contraction." (PMID 28678840, 2017). "RHOA also involved in renal integrity in diabetic mice, and its inhibitors attenuate diabetic nephropathy in different models of diabetes." (PMID 27846294, 2016). "RhoA also is involved in renal integrity in diabetic mice; its inhibitors attenuate diabetes-induced renal hypertrophy in different models of diabetes, including db/db mice, supporting a role for RhoA/Rho kinase in diabetes-associated nephropathy." (PMID 27649495, 2016). "Excessive activation of the RHOA/ROCK signaling pathway plays an important role in the development of the chronic complications of diabetes." (PMID 27846294, 2016). "Recently we reported that the RhoA/ROCK pathway contributes to cardiac dysfunction in diabetes at least in part by promoting the sustained activation of PKCβ2 and the production of reactive oxygen species, through a positive feedback loop involving iNOS." (PMID 24466133, 2014). "Diabetes is known to increase RhoA expression, the upstream regulator of ROCK, as shown in the basilar artery membrane at 2 weeks and aortic homogenates at 4-weeks post STZ in diabetic rodents." (PMID 24059472, 2013). "Our previous studies demonstrated significant upregulation of the active RhoA that positively correlated with increases in peroxynitrite as well as vascular permeability and impaired vasorelaxation in models of experimental diabetes." (PMID 21052489, 2010). "Our goal is to examine the effects of decomposing peroxynitrite and to explore the possible role of RhoA in modulating eNOS expression in rat vessels and cultured aortic endothelial cells in response to diabetes and hyperglycemia, respectively." (PMID 21052489, 2010). "Additionally, activated RhoA/Rho kinase (ROCK) mediates diabetes-induced elevation of arginase expression and activity, which contributes to impaired CC relaxation probably through the activation of p38 MAPK." (PMID 36338341, 2022). "Normal-Exos and miR-140-3p overexpressed-Exos accelerated diabetic wound healing by promoting the osteoblastogenesis function of BMSCs through inhibition plexin B1 expression which is the receptor of Sema4D and the plexin B1/RhoA/ROCK pathway compared with diabetes mellitus-Exos." (PMID 35236339, 2022). "Peroxynitrite also increases active RhoA in models of experimental diabetes." (PMID 33803946, 2021). "Evidence from literature indicates that diabetes upregulates the Ras-related small G protein RhoA, a factor that may impair cardiac function determining uncoupled eNOS, reduced NO bioavailability, and enhanced O2-." (PMID 34277669, 2021). "Our studies provided a link between oxidative stress, miR-133a, and RhoA in diabetes-induced hypercontraction and demonstrated that oxidative stress in response to hyperglycemia causes a decrease in miR-133a expression leading to upregulation of RhoA/Rho kinase pathway." (PMID 28678840, 2017).